HS3ST3B1 (heparan sulfate-glucosamine 3-sulfotransferase 3B1)
Description:
Sulfotransferase that utilizes 3'-phospho-5'-adenylyl sulfate (PAPS) to catalyze the transfer of a sulfo group to an N-unsubstituted glucosamine linked to a 2-O-sulfo iduronic acid unit on heparan sulfate. Catalyzes the O-sulfation of glucosamine in IdoUA2S-GlcNS and also in IdoUA2S-GlcNH2. The substrate-specific O-sulfation generates an enzyme-modified heparan sulfate which acts as a binding receptor to Herpes simplex virus-1 (HSV-1) and permits its entry. Unlike HS3ST1/3-OST-1, does not convert non-anticoagulant heparan sulfate to anticoagulant heparan sulfate.
Synonyms: 3-OST-3B; h3-OST-3B; 3OST3B1; 30ST3B1
Tractability: Antibody: its Gene Ontology location is reachable by antibodies, with high confidence; UniProt predicts a signal peptide or a membrane-spanning region.
Gene: Protein-coding gene on chromosome 17 (14,301,081 to 14,349,404, forward strand). Ensembl gene ENSG00000125430.
Subcellular location: Golgi apparatus membrane
Subcellular location (Human Protein Atlas): Vesicles
Pathways (Reactome):
Metabolism: HS-GAG biosynthesis
Gene Ontology:
Molecular function: [heparan sulfate]-glucosamine 3-sulfotransferase activity; sulfotransferase activity
Biological process: glycosaminoglycan biosynthetic process; heparan sulfate proteoglycan biosynthetic process; branching involved in ureteric bud morphogenesis
Cellular component: Golgi membrane; plasma membrane
Genetic constraint (gnomAD): Loss-of-function variants: 11 observed, 11.68 expected, observed/expected ratio (o/e) 0.94, 90% interval 0.59 to 1.55. The upper end of that interval is the gene's LOEUF score, 1.55, which puts it in group 6 of 6, group 1 being the genes least tolerant of losing a copy. Missense variants: 369 observed, 350.74 expected, observed/expected ratio (o/e) 1.05, 90% interval 0.96 to 1.15. Synonymous variants: 183 observed, 159.85 expected, observed/expected ratio (o/e) 1.14, 90% interval 1.01 to 1.29.
Homologues: Orthologues: chimpanzee HS3ST3B1 (99% identical), macaque HS3ST3B1 (99% identical), dog HS3ST3B1 (94% identical), guinea pig HS3ST3B1 (93% identical), pig HS3ST3B1 (90% identical), rabbit HS3ST3B1 (89% identical), mouse Hs3st3b1 (88% identical), rat Hs3st3b1 (88% identical), zebrafish hs3st3b1a (57% identical), zebrafish si:dkey-121b10.7 (57% identical), tropical clawed frog XB5817455 (31% identical), zebrafish hs3st1l2 (30% identical), and 2 more. Paralogues in human: HS3ST3A1 (76% identical), HS3ST4 (57% identical), HS3ST2 (55% identical), HS3ST6 (53% identical), HS3ST5 (35% identical), HS3ST1 (31% identical), NDST1 (31% identical), NDST3 (29% identical), NDST4 (29% identical), NDST2 (29% identical).
Diseases named in the same sentence as HS3ST3B1 in open-access papers:
HS3ST3B1 is named in the same sentence as 13 diseases in open-access papers, as found by Europe PMC text mining. Sharing a sentence is not in itself a finding about the gene and the disease. The quoted sentences say what the papers report.
metastatic tumors (2 papers, 2015 to 2018). "Interestingly, alterations were found in only non-metastatic tumors, affecting N-sulfation, and the isoforms of heparan sulfate 6-O-sulfotransferase 1 (HS6ST1), heparan sulfate-glucosamine 3-sulfotransferase 3B1 (HS3ST3B1) and heparan sulfate-glucosamine 3-sulfotransferase 5 (HS3ST5)." (PMID 30197623, 2018).
astrocytoma (1 paper, 2017). "Moreover, high expression of 7 of the high-malignant genes (C7ORF46, DUSP4, HS3ST3B1, ODZ1, TTL, VAV3, ZDHHC23) or low expression of 4 of the low-malignant genes (AKR1C3, ARHGEF10L, SMAD7, ST3GAL6) was associated with a lower progression free survival probability of grade III astrocytoma patients." (PMID 29152145, 2017).
malaria (1 paper, 2016). Malaria is a serious and sometimes fatal disease caused by a parasite that commonly infects a certain type of mosquito which feeds on humans. "Two of these (CDH13 and HS3ST3B1) have previously been shown to be malaria-associated and both are involved in glycoprotein-mediated cell-adhesion pathways that are widely implicated in the pathogenesis of malaria." (PMID 26744416, 2016). "In contrast, two of the random SNPs that had highly significant correlations (P < 0.01) were in genes previously linked to malaria resistance, namely, CDH13, encoding cadherin 13, and HS3ST3B1, encoding heparan sulfate 3-O-sulfotransferase 3B1." (PMID 26744416, 2016).
tumor (8 papers, 2018 to 2025). "Most of these genes are enzymes in the metabolism of tumor cells, such as HS3ST3B1, GLUD1, BCAT1, and ACAA2." (PMID 32280672, 2020). "Other potentially stiffness regulated genes were IL-33, HS3ST3B1, and IL-11, which were among the most differentially expressed genes between the PDECs grown in the soft matrix compared to the original uncultured stiff tumor." (PMID 40425576, 2025). "A review article described that the aberrant expression of HS3ST3B1 is observed in many cancers, and the authors posited that HS3ST3B1 may act as a tumor-promoting enzyme." (PMID 35574500, 2022). "Furthermore, we showed that DLEU1 executes its tumor-promoting functions by sponging tumor suppressor miR-99b and increasing the protein expression of oncogene HS3ST3B1 in BCA." (PMID 30984249, 2019).
cancer (5 papers, 2018 to 2022). A tumor composed of atypical neoplastic, often pleomorphic cells that invade other tissues. "Previous studies have shown that HS3ST3B1 was upregulated in several tumors and can maintain the mesenchymal phenotype and promote cancer cell proliferation and angiogenesis." (PMID 30984249, 2019). "To test whether DLEU1 exerts oncogenic functions in BCA by modulating the miR-99b/HS3ST3B1 axis, we investigated the effects of miR-99b or HS3ST3B1 on DLEU1-induced cancer cell proliferation, invasion, and cisplatin resistance." (PMID 30984249, 2019).
HS3ST3B1 also shares sentences with these, for which no sentence is quoted: bladder cancer (2 papers); non-small cell lung carcinoma (2); breast carcinoma (1); endotoxemia (1); leukemia (1); lung carcinoma (1); pancreatic cancer (1); skin cancer (1).